JKAMP (JNK1/MAPK8 associated membrane protein)
Description:
Regulates the duration of MAPK8 activity in response to various stress stimuli (By similarity). Facilitates degradation of misfolded endoplasmic reticulum (ER) proteins through the recruitment of components of the proteasome and endoplasmic reticulum-associated degradation (ERAD) system.
Synonyms: JAMP; C14orf100; CDA06; HSPC213; HSPC327; C24orf100; NEDSIL
Tractability: Antibody: UniProt predicts a signal peptide or a membrane-spanning region. PROTAC: UniProt records ubiquitination sites on it; ubiquitination databases record sites on it.
Gene: Protein-coding gene on chromosome 14 (59,484,443 to 59,505,410, forward strand). Ensembl gene ENSG00000050130.
Subcellular location: Endoplasmic reticulum membrane
Subcellular location (Human Protein Atlas): Vesicles; Nucleoplasm
Gene Ontology:
Molecular function: ubiquitin protein ligase binding
Biological process: ERAD pathway; response to unfolded protein
Cellular component: endoplasmic reticulum membrane; membrane
Genetic constraint (gnomAD): Loss-of-function variants: 6 observed, 17.5 expected, observed/expected ratio (o/e) 0.34, 90% interval 0.19 to 0.68. The upper end of that interval is the gene's LOEUF score, 0.68, which puts it in group 2 of 6, group 1 being the genes least tolerant of losing a copy. Missense variants: 153 observed, 221.83 expected, observed/expected ratio (o/e) 0.69, 90% interval 0.6 to 0.79. Synonymous variants: 72 observed, 77.54 expected, observed/expected ratio (o/e) 0.93, 90% interval 0.77 to 1.13.
Homologues: Orthologues: macaque JKAMP (99% identical), guinea pig JKAMP (98% identical), pig JKAMP (98% identical), mouse Jkamp (98% identical), rat Jkamp (98% identical), chimpanzee JKAMP (97% identical), zebrafish jkamp (83% identical), tropical clawed frog jkamp (81% identical), dog JKAMP (78% identical), rat Jkampl (73% identical), mouse Jkampl (70% identical), Drosophila melanogaster CG2126 (41% identical), and 1 more.
Diseases named in the same sentence as JKAMP in open-access papers:
JKAMP is named in the same sentence as 6 diseases in open-access papers, as found by Europe PMC text mining. Sharing a sentence is not in itself a finding about the gene and the disease. The quoted sentences say what the papers report.
diabetes (1 paper, 2025). "Furthermore, studies examining other systemic complications of diabetes, such as diabetic osteoporosis, have confirmed that the overexpression of JKAMP appears to mitigate the adverse effects of hyperglycemia through the activation of the Wnt signaling pathway." (PMID 40171194, 2025).
diabetic cardiomyopathy (1 paper, 2025). Diabetic cardiomyopathy is a disorder of the heart muscle in people with diabetes. "GET4 and JKAMP have recently been identified as valuable biomarkers in diabetic cardiomyopathy in type 1 diabetes." (PMID 41465472, 2025).
JKAMP also shares sentences with these, for which no sentence is quoted: cardiac hypertrophy (1 paper); Hyperglycemia (1); type 1 diabetes (1); vitiligo (1).